ABCB1 (ATP binding cassette subfamily B member 1)
Diseases named in the same sentence as ABCB1 in open-access papers (continued):
Sharing a sentence is not in itself a finding about the gene and the disease.
glioma (44 papers, 1995 to 2025). A benign or malignant brain and spinal cord tumor that arises from glial cells (astrocytes, oligodendrocytes, ependymal cells). "Among such transporters overexpressed in the BBB and glioma tumor cells are the P-glycoprotein multidrug resistance protein 1 (P-gp/MDR1/ABCB1) and the multidrug resistance-associated protein (MRP/ABCC1)." (PMID 33680961, 2021). "Thus, ABCB1 methylation can be regarded as a potential diagnostic or prognostic biomarker for glioma patients, indicating more aggressive tumors." (PMID 36233525, 2022). "Sixty glioma-associated targets were associated with CHR, such as MDR transporters (ABCB1, ABCC1, ABCG2), cyclin-dependent kinases (CDK1, CDK6), matrix metalloproteinases (MMP2, MMP9, MMP12), and genes related to inflammation or oxidative stress (NOS2, NOX4)." (PMID 40963691, 2025). "Abnormal expression of LUCAT1 affects glioma cell biology by regulating ABCB1 and promoting the activation of the RAS pathway." (PMID 39896807, 2024). "We also found that ABCB1 methylation is a frequent phenomenon in glioma samples; out of the 50 glioma samples analyzed, ABCB1 was found methylated in more than half of the samples." (PMID 36233525, 2022). "The results of this study show a high interindividual variability in the ABCB1 methylation level of the samples derived from gliomas of different grades." (PMID 36233525, 2022). "Regarding glioma research, the main focus has been placed on the role of ABCB1 on chemotherapy’s efficacy." (PMID 36233525, 2022). "The subject of epigenetic changes that are characteristic of ABCB1, including aberrant promoter methylation, is far less understood in glioma research." (PMID 36233525, 2022). "The results of this study indicate a high interindividual variability of ABCB1 methylation between glioma patients, which ranged from 0% to more than 50%." (PMID 36233525, 2022). "In this case, the degree of chemoresistance of C6 cells correlated with a decrease in the accumulation of doxorubicin in glioma cells expressing P-glycoprotein (ABCB1 protein)." (PMID 35056889, 2022). "Overexpression of CD133 also induced ABCB1 expression and activity leading to drug resistance in glioma." (PMID 31379943, 2019). "All these data supported a focal disruption of the BBTB in high-grade gliomas, which led to enhanced brain distribution of small-molecule drugs, which were subject to ABCB1 and/or ABCG2 efflux transport." (PMID 31832814, 2019). "Most tumors express ABCB1/P-gp in high levels, including schwannomas, meningiomas, low-grade gliomas (astrocytomas, pilocytic astrocytomas), and high-grade gliomas (GBMs, anaplastic astrocytomas, and anaplastic oligodendrogliomas)." (PMID 31878061, 2019). "The association of CD133 and ABC transporters has been observed by other investigators, who found that CD133(-) overexpressing glioma cells were drug resistant, in part due to the induction of ABCB1 expression and activity." (PMID 31379943, 2019). "In glioma, the most relevant ABC transporter proteins are p-glycoprotein (ABCB1), MDR-associated protein-1 (ABCC1), and breast cancer resistance protein (ABCG2)." (PMID 30123112, 2018). "For instance, paclitaxel accumulated to a greater extent in the metastatic gliomas, areas with low ABCB1 levels, compared to primary glioma as measured by MRI (magnetic resonance imaging)." (PMID 29186899, 2017). "We investigated levels of multiple drug resistance-related genes in U87 and primary glioma cells, including genes related to drug efflux (ABCB1, ABCC1, ABCC2, ABCC4, ABCG2, ATM), DNA damage repair (MGMT) and stemness (CD133)." (PMID 27486877, 2016). "Tie2 activation also promotes a chemoresistance phenotype in gliomas by inducing ABCB1 expression level and activity, and TGF-β1-mediated increase in Abcb1 expression and activity has been demonstrated in guinea pig brain endothelial cells in culture." (PMID 25698917, 2015).
glioma (continued). "ABCC3 is expressed more in differentiated glioma cells and regulates multidrug resistance, while ABCB1 and ABCC4 are important multidrug resistance factors." (PMID 25605243, 2015). "Before drug treatments, the expression ratios of drug-resistant ABC transporters in glioma cells (ABCB1 = 0.50 ± 0.06, ABCC1 = 0.26 ± 0.10, and ABCG2 = 0.57 ± 0.01) were evidently lower than those in GSCs (ABCB1, ABCC1 or ABCG2 = 1, respectively)." (PMID 25153726, 2014). "In a rat RG2 glioma model, tesmilifene reduced transendothelial electrical resistance and inhibited key efflux transporters—P-gp/ABCB1, BCRP/ABCG2, and MRP1—resulting in a 2.7-fold increase in fluorescein accumulation and enhanced albumin permeability within tumor tissue." (PMID 40806198, 2025). "This may partly be due to the heterogenic nature of the glioma stem cells, but also an elevation of drug transporters, such as ABCB1, that has been shown to be involved in acquired general drug resistance in cancer cells." (PMID 41331048, 2025). "In this study, we proposed ABCB1 methylation as a new valuable DNA methylation-based biomarker to stratify glioma patients according to the aggressiveness of the tumor, and to facilitate an accurate diagnosis and prognosis of gliomas." (PMID 36233525, 2022). "However, the clinical role of ABCB1 in glioma patients is still under investigation; specifically, its role as a biomarker is not yet clear." (PMID 36233525, 2022). "The methylation analysis revealed that ABCB1 is frequently methylated in the glioma samples." (PMID 36233525, 2022). "However, ABCB1 methylation in glioma samples remains elusive, and the potential clinical utility of its analysis is unclear to date." (PMID 36233525, 2022). "Importantly, the results of the Fisher–Freeman–Halton test revealed that ABCB1 was more frequently methylated in grade IV gliomas compared to grades II and III (p = 0.02514)." (PMID 36233525, 2022). "Thus, the aim of this study was to analyze the prevalence of ABCB1 methylation in gliomas of different grades and to verify the potential role of this epigenetic modification in glioma patients’ stratification." (PMID 36233525, 2022). "For comparison, we also measured the ABCB1 expression in glioma H4 cells." (PMID 33573093, 2021). "Interestingly, ABCB1 mRNA levels were higher in some gliomas than the control brain (Oncomine.org, accessed on 23 July 2017)." (PMID 29186899, 2017). "In addition to MGMT, we studied ABCB1 promoter methylation because ABCB1 is significantly expressed in glioma and discussed as a potential resistance factor." (PMID 24380367, 2013). "Since ABCB1 represents a multidrug resistance factor in several malignancies, including glioma, we additionally investigated the influence of ABCB1 promoter methylation on patients’ outcome by using a new established pyrosequencing assay to detect the methylation degree in the ABCB1 promoter." (PMID 24380367, 2013). "Interestingly, ABCA2 and ABCB1 (MDR-1/p-glycoprotein 1) were also more abundantly expressed by TdEC, reflecting the previously reported higher expression of p-glycoprotein 1 in EC from glioma than from normal brain." (PMID 18447899, 2008). "Thus, the aim of this study was to analyze the methylation level of the ABCB1 promoter in glioma patients of different WHO grades to establish its utility as a potential biomarker based on its relation to the IDH1 mutation status and other clinicopathological data." (PMID 36233525, 2022). "Thus, the aim of this study was to analyze the methylation of the ABCB1 promoter in tumor tissues from 50 glioma patients to verify its incidence and to semi-quantitively detect ABCB1 methylation levels in order to establish its utility as a potential biomarker." (PMID 36233525, 2022). "Thus, ABCB1 methylation can be regarded as a potential biomarker of glioma’s aggressiveness." (PMID 36233525, 2022). "More importantly, we also observed a significant correlation between ABCB1 methylation and a higher WHO grade of glioma." (PMID 36233525, 2022).
glioma (continued). "ABCB1/P-gp, ABCG2/BCRP, ABCC1/MRP1, ABCC4/MRP4, and ABCC5/MRP5 up-regulation has been observed in glioma cells at the mRNA and/or protein level; moreover, MRP3 de novo protein expression has also been detected in high grade gliomas (detailed below)." (PMID 31878061, 2019). "The high-grade glioma samples showed significantly higher levels of ABCC3/MRP3 and ABCB1/P-gp in the endothelial cells, but higher levels of ABCC1/MRP1, ABCC3/MRP3 and ABCC5/MRP5." (PMID 31878061, 2019). "In the following sections, we review the potential contributions of ABCB1 and ABCG2 in gliomas and medulloblastoma." (PMID 29186899, 2017). "Beside MGMT, the drug efflux transporters ABCB1 and ABCG2 are thought to affect survival of glioma patients due to their role in drug resistance." (PMID 24380367, 2013). "According to our best knowledge, such a role of ABCB1 methylation in glioma patients has not been studied." (PMID 36233525, 2022). "In fact, the promoter methylation of ABCB1 was found to be methylated in several tumor types, including gliomas, but its role as a biomarker is not fully established yet." (PMID 36233525, 2022). "In contrast to ABCG2, ABCB1 protein amounts in 60 CNS tumor samples, including several gliomas, revealed no significant change in expression compared to the normal brain parenchyma." (PMID 29186899, 2017). "In addition, it has been reported that ABCB1 is overexpressed in human glioma tissues and its expression level is strongly correlated with that of another glioma CSC marker CD133, suggesting the importance of ABCB1 in glioma CSCs." (PMID 27814696, 2016). "Due to its potential to penetrate the BBB without restriction by the ABCB1 and ABCG2 efflux transporters, the anti-glioma effects of this drug have been investigated." (PMID 36839989, 2023). "Among the WHO grade IV gliomas, the majority of the samples (63.33%) had methylated ABCB1, while in the WHO grade III it was less than half of the samples (46.66%); in the WHO grade II gliomas, none of the samples were found to be methylated in the ABCB1 promoter region." (PMID 36233525, 2022). "Neither ABCB1 nor ABCG2 expression was detected in the brain parenchyma under normal conditions, specifically astrocytes and glial cells, which are cells of origin for some gliomas." (PMID 29186899, 2017).
non-small cell lung carcinoma (43 papers, 1991 to 2026). A group of at least three distinct histological types of lung cancer, including non-small cell squamous cell carcinoma, adenocarcinoma, and large cell carcinoma. "The aim of this study was to assess the potential impact of the ABCB1 gene on the risk of non-small cell lung cancer development." (PMID 32277145, 2020). "This indicates that the presence of at least one T allele of polymorphism at the C3435T position of the ABCB1 gene is associated with an increased risk of developing non-small cell lung cancer." (PMID 32277145, 2020). "In this study, some newly diagnosed patients with non-small cell lung cancer was observed a rapid increase of the membrane expression level of ABCB1 in peripheral blood monocytes, after they received the first course of chemotherapy." (PMID 31830995, 2019). "Previously, we have shown that the response to PTX is augmented by resveratrol in ABCB1-overexpressing NCI-H60 non-small cell lung carcinoma." (PMID 27304668, 2016). "In non-small-cell lung cancer cells, ABCB1 mRNA levels can predict gemcitabine chemosensitivity." (PMID 27029062, 2016). "It was found that ABCB1, CXCR4, and FAK were overexpressed in non-small cell lung cancer (NSCLC) patients and cell lines." (PMID 37749625, 2023). "In a cellular model of non-small cell lung cancer (NSCLC), AIF-1 significantly inhibited ABCB1 activity, which was evaluated by the fluorimetric measurement of the intracellular accumulation of calcein." (PMID 36674503, 2023).
neuroblastoma (42 papers, 1991 to 2025). Neuroblastoma (NB) is the most common solid, extracranial childhood tumor. "Analysis by qPCR revealed high ABCB1 (the gene encoding Pgp) expression only in the SH-SY5Y neuroblastoma cells." (PMID 35955683, 2022). "High ABCB1 expression was also associated with favourable OS in neuroblastoma." (PMID 33202946, 2020). "In addition, ABCB1 expression may be an SNS-032-associated acquired resistance mechanism in neuroblastoma." (PMID 27517323, 2016). "In conclusion, our results help to elucidate the relationship between PHLDA1 and ABCB1 in human neuroblastoma." (PMID 41430389, 2025). "The level of ABCB1 following PHLDA1 silencing was assessed in another human neuroblastoma cell line, CHP-134." (PMID 41430389, 2025). "In this work, evidence of a more general mechanism of the induction of ABCB1 following PHLDA1 silencing was presented in vitro in two neuroblastoma cell lines, i.e., IMR-32 and CHP-134." (PMID 41430389, 2025). "Of the three, ABCB1 had the strongest difference between the groups, with a 3.3‐fold higher expression in neuroblastoma." (PMID 36181342, 2023). "A large-scale study using >100 neuroblastoma cell lines identified that ABCB1 or P-glycoprotein expression determines resistance to YM155 by their efflux pump activity." (PMID 35568716, 2022). "A significant amount of drug-adapted neuroblastoma cell lines displays increased ABCB1 activity, and ABCB1 has been previously shown to mediate YM155 resistance." (PMID 32131402, 2020). "In concert with previous studies, high ABCB1-expressing neuroblastoma cells generally displayed relatively low YM155 sensitivity." (PMID 32131402, 2020). "Although our data indicate that ABCB1 plays an important role in the cross-resistance of drug-adapted neuroblastoma cell lines to YM155, additional mechanisms are also involved." (PMID 32131402, 2020). "Limited information is available on ABCB1 expression as acquired drug resistance mechanism in neuroblastoma." (PMID 32131402, 2020). "Many drug-adapted neuroblastoma cell lines display enhanced ABCB1 activity, and drug-adapted cell lines have been shown to reflect clinically relevant resistance mechanisms." (PMID 32131402, 2020). "Here, we here investigated the effects of doxorubicin-loaded human serum albumin (HSA) nanoparticles in ABCB1-expressing neuroblastoma cells." (PMID 31501742, 2019). "Mechanistically, the synergy was based on a lapatinib induced inhibition of the multidrug-resistance efflux transporter ABCB1, which is frequently expressed in resistant neuroblastoma cells, which allowed prolonged and elevated cytotoxicity of YM155." (PMID 28596528, 2017). "The basal promoter of ABCB1 has several β-catenin/TCF4/LEF1-binding sites, suggesting that the canonical Wnt/β-catenin pathway regulates ABCB1, as shown in early colorectal, neuroblastoma and breast cancers." (PMID 28757546, 2017). "Only ABCB1-expressing neuroblastoma cell lines were insensitive to therapeutically achievable SNS-032 concentrations." (PMID 27517323, 2016). "In the presence of ABCB1 inhibitors, all 30 ABCB1-expressing neuroblastoma cell lines displayed SNS-032 IC50 values in the range of therapeutic SNS-032 concentrations." (PMID 27517323, 2016). "ABCB1 expression was the dominant SNS-032-resistance mechanism in neuroblastoma cells from a panel of 109 neuroblastoma cell lines." (PMID 27517323, 2016).
neuroblastoma (continued). "Beside this immediate blockade of ABCB1, we also observed reduced levels of ABCB1 in membranes from simvastatin-treated rhabdomyosarcoma and neuroblastoma cells." (PMID 26319048, 2016). "The cell surface expression of ABCB1 in SH-SY5Y neuroblastoma cells is significantly reduced for longer incubation times in the presence of simvastatin." (PMID 26319048, 2016). "Here, we show that simvastatin reduces endogenous dolichol levels and ABCB1 in human neuroblastoma SH-SY5Y cells." (PMID 26319048, 2016). "Statin treatment alters the glycosylation pattern of ABCB1 in neuroblastoma and rhabdomyosarcoma cells, similar to tunicamycin or PNGase F treatment." (PMID 26319048, 2016). "In order to quantify this effect, we here confirm significant reduction of cell surface ABCB1 protein expression in simvastatin-treated SH-SY5Y neuroblastoma cells by FACS analysis." (PMID 26319048, 2016). "In conclusion, we show that ABCB1 expression represents the predominant resistance mechanism in neuroblastoma cells with acquired resistance to SNS-032." (PMID 27517323, 2016). "This notion is further supported by our finding that SLC35F2 depletion increases the resistance of ABCB1-expressing neuroblastoma cells." (PMID 27735941, 2016). "In conclusion, we show that ABCB1 expression represents the primary (sometimes exclusive) resistance mechanism in neuroblastoma cells with acquired resistance to SNS-032." (PMID 27517323, 2016). "The Wnt receptor, Fzd1, was upregulated in a doxorubicin-resistant neuroblastoma cell line, and Fzd1-slienced drug-resistant cells had reduced ABCB1 expression levels and were sensitive to chemotherapeutic treatment." (PMID 25401518, 2014). "We tested a panel of 15 drugs for sensitization of neuroblastoma cells to the conventional chemotherapeutic vincristine, identifying tariquidar, an inhibitor of the transmembrane pump P‐glycoprotein (P‐gp/ABCB1), and the ERBB family inhibitor afatinib as the top resistance breakers." (PMID 36181342, 2023). "However, while ABCB1 is consistently upregulated in several cohorts of neuroblastoma cell lines and patient samples, other members of the ABC family are not regulated." (PMID 36181342, 2023). "YM155 also displayed synergistic action in neuroblastoma in in vitro and in vivo models in combination with lapatinib; the effect was attributed to lapatinib-induced inhibition of the ABCB1 efflux transporter, which allowed prolonged and elevated cytotoxicity of YM15543." (PMID 31591437, 2019). "Thus, the strong synergistic effect observed when lapatinib and YM155 were combined was inherent to ABCB1 expressing neuroblastoma cells, where ABCB1 inhibition by lapatinib augmented YM155 concentrations and cytotoxicity." (PMID 28596528, 2017). "Therefore, the combination of lapatinib and YM155 is a promising treatment option for neuroblastoma with either intrinsic or acquired ABCB1 upregulation." (PMID 28596528, 2017). "Moreover, induction of apoptosis and reduction of ABCB1 by simvastatin was evaluated in vivo by murine xenograft models with rhabdomyosarcoma and neuroblastoma cells." (PMID 26319048, 2016). "Besides the downregulation of ABCB1 and a direct inhibition of the transporter, simvastatin triggers also apoptosis in rhabdomyosarcoma and neuroblastoma cells." (PMID 26319048, 2016). "However, ABCB1 expression represents the dominant (sometimes exclusive) resistance mechanism to SNS-032 in neuroblastoma." (PMID 27517323, 2016).